SOCS3 (suppressor of cytokine signaling 3)
Diseases named in the same sentence as SOCS3 in open-access papers (continued):
Sharing a sentence is not in itself a finding about the gene and the disease.
adenoma (3 papers, 2010 to 2025). A neoplasm arising from the epithelium. "Logistic regression analysis was used to generate odds ratios (OR) and 95% confidence intervals to determine if low SOCS3 expression was associated with adenoma status." (PMID 20500855, 2010). "Based on these studies, we investigated SOCS3 mRNA expression in the normal mucosa of patients undergoing routine screening colonoscopy to determine if low SOCS3 predisposes to adenoma and could thus be considered an early biomarker of CRC risk." (PMID 20500855, 2010). "As SOCS3 has been shown to inhibit the actions of IL-6 and TNFα in the intestine, we hypothesized that decreased SOCS3 expression in normal mucosa may predispose to adenomas and thus increase risk for CRC." (PMID 20500855, 2010). "During the adenoma stage, SOCS3 is downregulated and inactivated, leading to sustained activation of STAT3; in advanced stages, it is further silenced through mechanisms such as CpG island methylation." (PMID 41376630, 2025). "Taken together with these studies, we conclude that SOCS3 silencing occurs later in the progression from adenoma to adenocarcinoma, and is not an independent, early biomarker of CRC risk in the normal mucosa." (PMID 20500855, 2010). "We examined SOCS3 mRNA levels in normal mucosa biopsies of 322 screening colonoscopy patients (93 with adenoma and 229 without adenoma) using real-time qRT-PCR." (PMID 20500855, 2010). "The current study tested the hypothesis that patients with adenoma may have lower SOCS3 in the normal mucosa than patients without adenoma, thus contributing to a permissive environment for aberrant growth." (PMID 20500855, 2010).
AIDS (3 papers, 2015 to 2024). A syndrome resulting from the acquired deficiency of cellular immunity caused by the human immunodeficiency virus (HIV). "It remains a possibility that the immunosuppressive effect of SOCS1 and/or SOCS3 may play a protective role against a potential immunopathology of experimental MCMV retinitis or AIDS-related HCMV retinitis." (PMID 31031749, 2019). "Although many questions remain, SOCS1 and/or SOCS3 may play promising roles in the balance of this phenomenon, potentially revealing themselves as novel therapeutic targets to improve the management and/or prevention of AIDS-related HCMV retinitis." (PMID 31031749, 2019). "Further studies utilizing knockdown or overexpression of SOCS1 or SOCS3 would elucidate this possibility for experimental MCMV retinitis and/or AIDS-related HCMV retinitis." (PMID 31031749, 2019). "If SOCS1 and/or SOCS3 contribute to the pathogenesis of this disease, then their inhibition in HIV/AIDS patients with HCMV retinitis could prevent further damage to affected eyes and/or protect the contralateral eye from vision loss." (PMID 31031749, 2019). "Herein we discuss these human and animal herpesviruses currently known to affect SOCS proteins in various in vitro and in vivo model systems, with particular emphasis on SOCS1 and SOCS3 expression during experimental MCMV retinitis, a mouse model used to study AIDS-related HCMV retinitis." (PMID 31031749, 2019).
cardiac hypertrophy (3 papers, 2021 to 2023). "Overall, these results indicate that SOCS3 modulates cardiac hypertrophy and function, likely by targeting GRP78-mediated ER stress and mitophagy." (PMID 33585485, 2021). "Together, these in vivo findings suggested that SOCS3 ablation aggravated cardiac hypertrophy and dysfunction by enhancing GRP78 and its downstream effectors." (PMID 33585485, 2021). "Overall, this study provides novel evidence that SOCS3 ablation accelerates cardiac hypertrophy and dysfunction after pressure overload, possibly through activation of ER stress and mitophagy pathways." (PMID 33585485, 2021). "Suppressor of cytokine signaling-3 (SOCS3) has been demonstrated to protect against cardiac hypertrophy and dysfunction, but its mechanisms are largely unknown." (PMID 33585485, 2021). "We next investigated the role of SOCS3 in cardiac hypertrophy in vitro." (PMID 33585485, 2021). "Indeed, SOCS3 regulates cardiac hypertrophy and dysfunction partially through gp130/JAK signaling after hypertrophic stimulation." (PMID 33585485, 2021). "Indeed, cardiac-specific knockout of SOCS3 (SOCS3cko) results in cardiac hypertrophy, chamber dilatation, and dysfunction accompanied by activation of gp130 signaling and abnormal myofilament Ca2+ sensitivity after pressure overload." (PMID 33585485, 2021). "In this study using primary cardiomyocytes, SOCS3cko mice, and rAAV9-injected wild-type mice, we identified a novel mechanism for SOCS3 to regulate cardiac hypertrophy and dysfunction through targeting of GRP78-mediated ER stress and mitophagy in a TAC-induced model." (PMID 33585485, 2021). "Conversely, adenovirus-mediated overexpression of SOCS3 in cardiomyocytes markedly inhibits the LIF and CT-1-induced hypertrophic response, as well as activation of gp130 downstream signals, suggesting that SOCS3 may be a new potential therapeutic target for treatment of cardiac hypertrophy and HF." (PMID 33585485, 2021). "Prolonged pressure overload significantly downregulated SOCS3 expression and reduced GRP78 ubiquitination and degradation, which resulted in activation of ER stress and mitophagy, thereby leading to cardiac hypertrophy, apoptosis and dysfunction." (PMID 33585485, 2021).
cardiomyopathy (3 papers, 2021 to 2025). A disease of the heart muscle or myocardium proper. "However, if Prmt7 is depleted after menopause, STAT3 signaling is dysregulated due to decreased negative feedback by Socs3, eventually resulting in more severe cardiomyopathy." (PMID 38486105, 2024).
cutaneous T cell lymphoma (3 papers, 2003 to 2019). "Indeed, constitutive SOCS-3 expression has been reported for cutaneous T-cell lymphoma lines, and reversal of this expression was associated with increased sensitivity to interferon γ inhibition of proliferation." (PMID 12888825, 2003). "Persistent expression of SOCS1 and/or SOCS3 is observed in several haematological malignancies such as cutaneous T cell lymphoma (CTCL), chronic myeloid leukemia (CML), ALK+ anaplastic large cell lymphoma (ALCL), and some acute leukemia." (PMID 24757565, 2014).
endothelial dysfunction (3 papers, 2021 to 2025). In vascular diseases, endothelial dysfunction is a systemic pathological state of the endothelium (the inner lining of blood vessels) and can be broadly defined as an imbalance between vasodilating and vasoconstricting substances produced by (or acting on) the endothelium. "Given that increased inflammatory response in EC is the major trigger for ALI, we were interested to determine if SOCS3 modulates endothelial dysfunction caused by inflammatory agents." (PMID 33372035, 2021). "The role of SOCS3 in protecting against inflammatory agonist-induced endothelial dysfunction was further validated in vivo." (PMID 33372035, 2021). "A potential role of SOCS3 as a major negative regulator of cytokine signaling in inflammatory agonist-induced endothelial dysfunction warrants further investigation." (PMID 33372035, 2021). "Using human lung ECs and EC-specific SOCS3 knockout mice, we tested the hypothesis that SOCS3 confers microtubule (MT)-mediated protection against endothelial dysfunction." (PMID 33372035, 2021).
epilepsy (3 papers, 2020 to 2024). A brain disorder characterized by episodes of abnormally increased neuronal discharge resulting in transient episodes of sensory or motor neurological dysfunction, or psychic dysfunction. "In addition, overexpression of BDNF in cortical neurons from Sip1 mice resulted in increased expression of Bcl-2, Socs3 and Stat3 genes, which may contribute to the protection of neurons from injury in epilepsy." (PMID 39408863, 2024).
gastric tumors (3 papers, 2019 to 2025). "On the other hand, leptin signaling could be inhibited by suppressor of cytokine signaling 3 (SOCO3), of which mice with SOCS3 conditional knockout in gastrointestinal epithelial cells develop gastric tumors that resemble human intestinal-type GC." (PMID 40357361, 2025). "T3b-SOCS3 cKO mice showed spontaneous gastric tumor by enhancing the ObRb-STAT3 pathway." (PMID 31141984, 2019). "In contrast, in T3b-SOCS3 cKO mice, CD45+ infiltrated cells clearly appeared at 15 weeks of age, when gastric tumor formation was already completed." (PMID 31141984, 2019). "Furthermore, expression of mRNA transcripts for the bona fide STAT3‐target genes Socs3, Icam1, and Reg3a, which are both induced by IL11 in gastric tumors, were significantly decreased in tumors from bazedoxifene‐treated animals." (PMID 30885958, 2019).
glaucoma (3 papers, 2016 to 2024). Increased pressure in the eyeball due to obstruction of the outflow of aqueous humor. "There was a clear upregulation of inflammatory/immune response genes in the retina detectable at the earliest glaucoma time point, including Gfap, Osmr, Fgf2, Edn2, Stat3, and Socs3." (PMID 37762022, 2023). "To determine whether IL-6-mediated changes in gp130 signaling impact the inflammatory, cell survival and gp130-related regulatory response of the retina to glaucomatous stressors, we examined gene expression of Tnfα, lL-1β,Bcl-xl, Bax and Socs3 in the Microbead Occlusion Model of murine glaucoma." (PMID 27747134, 2016).
Hodgkins lymphoma (3 papers, 2014 to 2022). A heterogeneous group of malignant lymphoid neoplasms of B-cell origin characterized histologically by the presence of Hodgkin and Reed-Sternberg (HRS) cells in the vast majority of cases. "In support of this role, SOCS-3 overexpression reportedly diminishes proliferation of classical Hodgkin lymphoma cell lines, whereas its loss has been postulated to predispose for the emergence of a more aggressive disease." (PMID 24883303, 2014).
liver diseases (3 papers, 2010 to 2022). "Our results support earlier findings that SOCS3 polymorphisms influence liver disease progression by modulating the SOCS3 protein expression and thus down-regulate the JAK/STAT signaling." (PMID 28179578, 2017). "In this study, we investigated the possible association of SOCS3 promoter variants with the progression of HBV-related liver diseases and SOCS3 methylation with HBV-induced HCC." (PMID 28179578, 2017). "This shows that SOCS3 gene polymorphisms and methylation play an important role in the regulation of SOCS3 expression, affecting the progression of HBV‐associated liver diseases." (PMID 36169255, 2022). "Therefore, this study aims to investigate whether SOCS3 promoter variants are associated with HBV infection and HBV-related liver diseases and to investigate the hypermethylation in the SOCS3 promoter region and corresponding SOCS3 mRNA expression in HBV-related HCC." (PMID 28179578, 2017). "This first study reports on the association of SOCS3 variants with HBV susceptibility and progression of HBV-related liver diseases." (PMID 28179578, 2017). "In conclusion, the SOCS3 promoter variants rs111033850 and rs12953258 are associated with HBV infection and HBV-related liver diseases." (PMID 28179578, 2017). "We showed that the SOCS3 promoter variants are associated with HBV infection and HBV-related liver diseases." (PMID 28179578, 2017). "Nevertheless, it is of interest to elucidate the precise function of SOCS3 in TLR response, since accumulating evidence suggests that SOCS3 is important for the pathology of hepatic diseases." (PMID 20862390, 2010). "In this case, this supports the notion that SOCS3 affects the progression of liver disease." (PMID 36169255, 2022). "Although our data indicate that SOCS3 expression is associated with HBV infection and may involve in the progression of HBV-related liver diseases, the study has several limitations." (PMID 28179578, 2017). "Thus, while further studies are required, SOCS3 could be an attractive target for the therapy of human liver diseases." (PMID 20862390, 2010). "However, SOCS3 expression in tumor and adjacent non-tumor tissues was not significantly different, suggesting that other factors such as phosphorylation, acetylation and microRNAs may also involve in the regulation of SOCS3 expression during progression of liver diseases." (PMID 28179578, 2017). "Our study suggests that SOCS3 polymorphisms and methylation play an important role in regulation of SOCS3 expression and thus influences the progression of HBV-related liver diseases." (PMID 28179578, 2017). "However, there are so far no available data on association of SOCS3 promoter variants with susceptibility to HBV infection and the clinical course of HBV-related liver diseases." (PMID 28179578, 2017). "Due to the study design as a case-control study, SOCS3 expression over the course of HBV infection were not assessed longitudinally and therefore the causative effect of SOCS3 expression on progression of HBV-related liver diseases could not conclusively be determined." (PMID 28179578, 2017).
lung disease (3 papers, 2010 to 2020). "Reduced expression of SOCS3 has been associated with recurrent and pulmonary disease in TB patients, respectively." (PMID 29176982, 2017). "Because SOCS3 has been proposed as a mechanism of IL-10–mediated protection against inflammatory processes in other models of lung disease, we asked whether SOCS3 was differentially expressed in Il10−/− and Il10+/+ mice." (PMID 20826374, 2010).
lupus (3 papers, 2018 to 2025). "CD4+ T cells from lupus patients have higher expression of IL-17 and SOCS3 than healthy controls, with positive correlation between IL-17 levels and SOCS3 expression." (PMID 33271810, 2020). "This suggests that SOCS3 could potentially mitigate kidney damage arising from complications related to systemic lupus erythematosus by modulating immune responses and inflammatory processes." (PMID 40755762, 2025). "Blocking the G-CSF-R pathway or enhancing negative regulators of G-CSF-R pathway, such as p38 MAPK, ERK, and SOCS3, in lupus-prone mouse models could serve as a proof of concept to validate the involvement of the G-CSF pathway in lupus pathogenesis." (PMID 29868014, 2018).
myocardial ischemia (3 papers, 2015 to 2023). A disorder of cardiac function caused by insufficient blood flow to the muscle tissue of the heart. "Based on results in cardiac-specific SOCS3-KO mice, SOCS3 was suggested to represent a key factor that exacerbates the development of myocardial ischemia/reperfusion injury." (PMID 37160311, 2023). "Here, we aimed to determine whether cardiac SOCS3 deficiency and IPC would synergistically reduce infarct size after myocardial ischemia reperfusion injury." (PMID 34292971, 2021). "In our present study, we observed prompt SOCS3 induction in heart tissue after IC, which was induced by a brief episode of nonlethal myocardial ischemia and reperfusion." (PMID 34292971, 2021).
nephritis (3 papers, 2008 to 2018). Inflammation of renal tissue. "Local delivery of IL-4 to inflamed glomeruli has a major effect on reducing the number of SOCS3-expressing glomerular macrophages, and this is reflected by a decrease in the severity of nephritis, supporting a role for SOCS3 in driving M1-mediated injury." (PMID 25120543, 2014). "Increased levels of transcripts for pathway members including JAK3, STAT3, SOCS3, PTPN1, CDKN1A, RRAS and MAPK1 were observed in nephritis." (PMID 18980674, 2008). "Additionally, M1 macrophages have shown an impaired proinflammatory effect and an enhanced anti-inflammatory effect in the absence of SOCS3 in a nephrotoxic nephritis model, thus indicating an essential role of SOCS3 in the development of M1 macrophages." (PMID 29950923, 2018).
nonalcoholic fatty liver disease (3 papers, 2022 to 2025). "For instance, in “Non-alcoholic fatty liver disease” pathway, IL6 activates its receptor IL6R and regulates the activity of lipogenic enzymes through SOCS3 and SREBP-1c to influence de novo fatty acid synthesis." (PMID 35237299, 2022). "This technology has been used to silence genes crucial for adipocyte differentiation, such as PPARG and FKBP5, as well as to target three genes (SOCS3, DUSP1, and SIK1) that are upregulated in the adipose tissue of patients with nonalcoholic fatty liver disease (NAFLD)." (PMID 39684387, 2024).
oral cancer (3 papers, 2012 to 2021). "In the present study we show that altered subcellular localization is an additional mechanism of SOCS3 loss of function in oral cancer cells." (PMID 23028842, 2012). "Inhibition of endogenous SOCS3 significantly reduced the MPT0B098-induced apoptosis in oral cancer cells, whereas overexpression of SOCS3 induced the apoptosis." (PMID 27367272, 2016).
peripheral nerve injury (3 papers, 2012 to 2019). Injury to a peripheral nerve. "Real-time PCR showed that the markedly enhanced levels of SOCS3 mRNA were associated with peripheral nerve injury." (PMID 23365595, 2012). "Using gliotropic lentiviral vectors in a rat model of peripheral nerve injury, Jak-Stat3 pathway was inhibited by Socs3, in a negatively feedback fashion, resulting in a decrease in neuroinflammation and mechanical allodynia." (PMID 24098399, 2013).
polycystic ovary syndrome (3 papers, 2021 to 2024). A disorder that manifests as multiple cysts on the ovaries. "Finally, with regard to direct effects of altered leptin signaling components in oocyte maturation, SOCS3 mRNA was shown to be decreased in human CC collected from patients with polycystic ovary syndrome (PCOS)." (PMID 33924072, 2021).
polycythemia vera (3 papers, 2016 to 2022). "Finally, a F136L germline SOCS3 mutation found in a subset of polycythemia vera patients has been shown to display an impaired capacity to inhibit erythropoietin receptor-JAK2 signalling." (PMID 29330478, 2018). "Similarly, it has been reported that the histone deacetylase inhibitor vorinostat induces apoptosis by reactivation of SOCS1 and SOCS3 in polycythemia vera (PV)." (PMID 35611249, 2022).
preeclampsia (3 papers, 2020 to 2022). Preeclampsia is a hypertensive disorder of pregnancy that is characterized by new-onset hypertension with proteinuria presenting after 20 weeks of gestation, and depending on mild or severe forms may initially present with severe headache, visual disturbances, and hyperreflexia. "We also found that increased IL-6 and sgp130 levels are associated with reduced suppressor of cytokine signaling-3 (SOCS-3) expression in both maternal vessel endothelium and circulating neutrophils in preeclampsia." (PMID 35366257, 2021). "Downregulated SOCS3 in trophoblasts may lead to weaker inhibitory effects of cytokines on the placentas of patients with preeclampsia, which may account for the increased placental inflammatory response in preeclampsia." (PMID 36587196, 2022). "Because sgp130 binds to sIL-6R/IL-6 and blocks sIL-6R/IL-6 trans-signaling-induced endogenous anti-inflammatory activity in endothelial cells (such as SOCS-3 induction), increased sgp130 production could be considered an indicator of reduced anti-inflammatory activity in preeclampsia." (PMID 35366257, 2021).
pulmonary arterial hypertension (3 papers, 2019 to 2023). Pulmonary arterial hypertension (PAH) is a group of diseases characterized by mean pulmonary artery pressure >20 mmHg and elevated pulmonary arterial resistance leading to right heart failure. "This approach was used in a paper from this year that shows significant upregulation of SOCS3, ITGAL, NFIC, NCOR2, and PGK1 mRNA (qRT-PCR) in peripheral blood mononuclear cells from pulmonary arterial hypertension (PAH) patients compared to healthy controls (p ≤ 0.05)." (PMID 37762023, 2023).